NOTUM (notum, palmitoleoyl-protein carboxylesterase)
Description:
Carboxylesterase that acts as a key negative regulator of the Wnt signaling pathway by specifically mediating depalmitoleoylation of WNT proteins. Serine palmitoleoylation of WNT proteins is required for efficient binding to frizzled receptors.
Synonyms: hNOTUM
Tractability: Small molecule: a structure with a bound ligand is known; a high-quality ligand is known. Antibody: its Gene Ontology location is reachable by antibodies, with high confidence; UniProt places it where antibodies can reach, with medium confidence; UniProt predicts a signal peptide or a membrane-spanning region. PROTAC: a small molecule that binds it is known.
Target class: Enzyme; Hydrolase
Gene: Protein-coding gene on chromosome 17 (81,952,507 to 81,963,328, reverse strand). Ensembl gene ENSG00000185269.
Subcellular location: Secreted
Subcellular location (Human Protein Atlas): Endoplasmic reticulum; Predicted to be secreted
Pathways (Reactome):
Metabolism of proteins: Post-translational protein phosphorylation; Regulation of Insulin-like Growth Factor (IGF) transport and uptake by Insulin-like Growth Factor Binding Proteins (IGFBPs)
Signal Transduction: Release of Hh-Np from the secreting cell
Gene Ontology:
Molecular function: palmitoleyl hydrolase activity; protein binding; phospholipase C activity; protein-containing complex destabilizing activity; hydrolase activity; hydrolase activity, acting on ester bonds; lipase activity
Biological process: bone development; negative regulation of Wnt signaling pathway; protein depalmitoleylation; regulation of bone mineralization; negative regulation of canonical Wnt signaling pathway
Cellular component: endoplasmic reticulum lumen; extracellular region
Genetic constraint (gnomAD): Loss-of-function variants: 33 observed, 50.55 expected, observed/expected ratio (o/e) 0.65, 90% interval 0.49 to 0.87. The synonymous counts are far from expectation, so gnomAD's model fits this gene poorly and the ratio says little. Missense variants: 638 observed, 631.71 expected, observed/expected ratio (o/e) 1.01, 90% interval 0.95 to 1.08. Synonymous variants: 347 observed, 271.44 expected, observed/expected ratio (o/e) 1.28, 90% interval 1.17 to 1.4.
Homologues: Orthologues: chimpanzee NOTUM (99% identical), macaque NOTUM (97% identical), pig NOTUM (95% identical), dog NOTUM (95% identical), guinea pig NOTUM (92% identical), mouse Notum (91% identical), rat Notum (91% identical), zebrafish notum1a (73% identical), tropical clawed frog notum (61% identical), zebrafish notum1b (7% identical).
Diseases named in the same sentence as NOTUM in open-access papers:
NOTUM is named in the same sentence as 26 diseases in open-access papers, as found by Europe PMC text mining. Sharing a sentence is not in itself a finding about the gene and the disease. The quoted sentences say what the papers report.
colorectal cancer (5 papers, 2021 to 2024). A primary or metastatic malignant neoplasm that affects the colon or rectum. "NOTUM encodes palmitoleoyl-protein carboxylesterase, which is involved in the proliferation and migration of colorectal cancer and proposed as a diagnostic and therapeutic candidate." (PMID 36293321, 2022). "APC mutant colorectal cancer cells secrete WNT antagonists such as NOTUM, which repress wild-type ISCs." (PMID 39060237, 2024). "Recently, NOTUM has been reported to regulate cancer development in numerous tumor types, including invasive urothelial carcinoma of the bladder and colorectal cancer." (PMID 34402722, 2021). "NOTUM is overexpressed in hepatocellular carcinoma, gastric cancer, invasive urothelial carcinoma of the bladder and colorectal cancer." (PMID 34402722, 2021). "NOTUM acts as a key negative regulator of the Wnt signaling pathway, and knockdown of NOTUM genes inhibits the proliferation and migration of colorectal cancer cells." (PMID 34604089, 2021). "In the same time, there is a research showing that NOTUM is overexpressed in primary colorectal cancer, gastric cancer, liver cancer, breast cancer, lung cancer, ovarian cancer and endometrial cancer." (PMID 34852762, 2021).
colon carcinoma (2 papers, 2021 to 2023). "NOTUM, which encodes for a palmitoleoyl-protein carboxylesterase being overexpressed in colon tumors and supporting tumor initiation and proliferation, was also found to be downregulated upon BHLHE40 ablation." (PMID 36890812, 2023). "NOTUM protein and mRNA expression levels in colon carcinoma tissues were increased (P < 0.05), compared with those in para-tumor tissue." (PMID 34402722, 2021). "As the knockdown of NOTUM could regulate colon carcinoma development and apoptosis in vitro, this process was also examined in vivo." (PMID 34402722, 2021). "NOTUM protein and mRNA expression levels in colon carcinoma tissues and RKO cells were increased." (PMID 34402722, 2021). "This suggests that NOTUM may be involved in the development and progression of colon cancer." (PMID 34402722, 2021).
hepatocellular carcinoma (2 papers, 2015 to 2021). A malignant tumor that arises from hepatocytes. "Originally discovered in fruit flies in screens for genes that interact with the Wnt protein Wingless, NOTUM gene encodes a secreted hydrolase, which has recently been identified in hepatocellular carcinoma with mutant β-catenin." (PMID 26517809, 2015).
Obesity (2 papers, 2018 to 2021). Accumulation of substantial excess body fat. "Our current findings show that long-term NOTUM overexpression in the liver protects against diet-induced obesity and improved glucose homeostasis in mice." (PMID 34385484, 2021). "We now report studies of chronic overexpression of NOTUM in liver indicating that it protects against diet-induced obesity and improves glucose homeostasis in mice." (PMID 34385484, 2021). "In summary, our study demonstrates that NOTUM overexpression in the liver protects against diet-induced obesity and improves glucose homeostasis in mice, probably through enhanced thermogenic capacity and decreased fibrosis and inflammation in the adipose tissue." (PMID 34385484, 2021).
intrauterine growth restriction (1 paper, 2024). "Previous work showed that decreased NOTUM expression activated the Wnt pathway and inhibited stem cell differentiation of human trophoblast cells, ultimately resulting in PE and intrauterine growth restriction." (PMID 38765115, 2024).
osteoporosis (1 paper, 2019). A condition of reduced bone mass, with decreased cortical thickness and a decrease in the number and size of the trabeculae of cancellous bone (but normal chemical composition), resulting in increased fracture incidence. "Sclerostin, encoded by Sost, is an established osteoporosis drug target while NOTUM is a novel osteoporosis drug target." (PMID 30622831, 2019). "Since NOTUM is a potential cortical bone specific osteoporosis target, we selected Notum−/− mice for further analyses." (PMID 30622831, 2019). "To evaluate the effect of orally active small molecule NOTUM inhibition on bone mass in an established osteoporosis disease model, we studied OVX rats starting at 14 months of age." (PMID 30622831, 2019).
ovarian tumors (1 paper, 2024). "When BRCA2mt ovarian tumors were compared with BRCA1mt tumors, eight genes (NOTUM, SFRP5, RNF43, ZNRF3, DKK1, DKK4, NKD1, and AXIN2) that negatively regulate Wnt signaling were upregulated in BRCA2mt tumors." (PMID 39028933, 2024).
tumor (17 papers, 2016 to 2026). "The dysregulated Wnt antagonists SFRP1 and NOTUM were found at the Q–A transition, and independent overexpression of either induced a pronounced astrocytic shift in tumor cell morphology, transcriptome, and methylome." (PMID 40770193, 2025). "Most importantly, as NOTUM is a secreted protein and its levels in blood correlate with tumor growth, it has potential as a pharmacodynamic biomarker for PORCN and other Wnt pathway inhibitors." (PMID 26848981, 2016). "As NOTUM expression is up-regulated in tumors and may be correlated with tumor progression, NOTUM expression was blocked using a NOTUM knockdown lentivirus in vitro to examine the effects." (PMID 34402722, 2021). "Strikingly, they found that ligand-dependent tumours tend to silence genes encoding Wnt antagonists, such as AXIN2, NKD1, APCDD1, NOTUM, and DKK4, whereas ligand-independent tumours effectively bypass Wnt-pathway negative feedback loops without the need for such selective pressure." (PMID 33673710, 2021). "The embryonal HBTOs were enriched with WNT target genes and EMT markers, including AXIN2, LEF1, DKK1, NOTUM, NKD1 and VIM, in line with the embryonal tumor signature." (PMID 39567475, 2024). "These cells also expressed general WNT target genes, such as NOTUM and NKD1, but at a lower level than the embryonal tumor cluster." (PMID 39567475, 2024). "Consistently, we demonstrate that NOTUM is highly expressed in human CRC and its expression positively correlates with the expression of FASN in tumor tissues." (PMID 39404424, 2024). "NOTUM expression in COAD, ESCA, READ and STAD tumor tissues was significantly higher compared with that in normal tissues, especially in COAD and READ." (PMID 34402722, 2021). "The current results suggested that NOTUM expression in COAD, ESCA, READ and STAD tumor tissues was higher compared with that in normal tissues, especially in COAD and READ." (PMID 34402722, 2021). "Analysis of leading-edge genes within the NR signature identified five consensus differentially expressed NRs in the two discovery cohorts, all expressed at a significantly higher level in LI versus LD tumours—AXIN2, NKD1, APCDD1, NOTUM and DKK4." (PMID 31563876, 2020). "Supporting the notion that these modules represent specific signatures, genes known to be expressed in tumour epithelium, such as WNT targets (e.g. AXIN2, NOTUM), FGF3 and BMP4 were contained in the brown module [Suppl." (PMID 29541918, 2018). "In addition to regions exhibiting fetal tumor characteristics, we also identified areas with embryonal tumor features in this tissue, characterized by high levels of WNT target genes such as NOTUM, DKK1/4, NKD1, APCDD1." (PMID 39567475, 2024). "We constructed a novel seven-gene signature (B3GALT5-AS1, DNER, CSN1S1, KIF5A, SIX3, NOTUM, and CPS1) and a combined prognostic model integrating a seven-gene signature with patient age and tumor size to quantify the likelihood of distant metastasis in lymph node-negative TNBC." (PMID 34604089, 2021).
cancer (9 papers, 2016 to 2026). A tumor composed of atypical neoplastic, often pleomorphic cells that invade other tissues. "In this study we identify Notum as a potential biomarker for Wnt driven cancers and show that coordinate regulation of NOTUM and AXIN2 expression may be a useful predictor of response to PORCN inhibitors." (PMID 26848981, 2016). "Since the deregulation of Wnt pathway plays an important role not only in the development of many different tumors, but also to the resistance of cancer cells to anticancer drugs, the upregulation of NOTUM by TTFields might have a therapeutic effect against resistant tumors." (PMID 35840560, 2022). "The down-regulated genes included palmitoleoyl-protein carboxylesterase (NOTUM), which is known to affect the Wnt signaling pathway, and serpin family B member 2 (SERPINB2), a gene related to autophagy and senescence in cancer." (PMID 38541076, 2024). "The differences in cell differentiation and cancer-related genes (AFP, NOTCH1, CSF1, NOTUM, TGFβ, and vimentin genes) implied different biological characteristics between cells cultured in the 3D and 2D models." (PMID 32582546, 2020). "Among the cancer-specific states, we identified a stem-like state absent in the healthy colon, characterized by upregulation of WNT antagonists, including NOTUM, NKD1, and APCDD1." (PMID 40393458, 2025).
NOTUM also shares sentences with these, for which no sentence is quoted: dentin dysplasia (2 papers); gastric cancer (2); ovarian carcinoma (2); adenoma (1); bladder cancer (1); breast carcinoma (1); colon adenocarcinoma (1); digestive system carcinoma (1); endometrial cancer (1); hypotrichosis simplex (1); invasive urothelial carcinoma of the bladder (1); liver cancer (1); lung carcinoma (1); osteoarthritis (1); osteosarcoma (1); periapical abscess (1); type 2 diabetes mellitus (1).